TCF21 (transcription factor 21)
Diseases named in the same sentence as TCF21 in open-access papers (continued):
Sharing a sentence is not in itself a finding about the gene and the disease.
liver cancer (1 paper, 2020). An epithelial or non-epithelial malignant neoplasm that arises from the liver. "Transfer of miR‐25‐3p by CHB‐PNALT‐Exo promoted the development of liver cancer by inhibiting the co‐expression of TCF21 and HHIP." (PMID 32525231, 2020). "The expression of HHIP was significantly positively correlated with TCF21 expression in HBV‐positive patients with liver cancer and CHB patients with PNALT (≥A2)." (PMID 32525231, 2020). "Exosomes secreted by CHB patients with PNALT and liver tissue inflammation grade ≥ A2 promoted the development of liver cancer by transferring miR‐25‐3p to inhibit the co‐expression of TCF21 and HHIP." (PMID 32525231, 2020). "TCF21 and HHIP are two target genes of miR‐25‐3p that have anti‐tumour effects in HBV‐positive liver cancer." (PMID 32525231, 2020). "The results showed that TCF21 directly interacted with HHIP and was positively correlated with HHIP in CHB patients with PNALT and HBV‐positive patients with liver cancer." (PMID 32525231, 2020). "The expression of TCF21 and HHIP was negatively correlated with miR‐25‐3p expression in HBV‐positive patients with liver cancer." (PMID 32525231, 2020). "Therefore, both TCF21 and HHIP, which were identified as target genes of miR‐25‐3p and were downregulated in liver cancer, were used to follow up studies." (PMID 32525231, 2020). "This shows that TCF21 and HHIP have synergistic effects on the viability, proliferation, apoptosis, invasion and migration of HepG2.2.15 cells and both TCF21 and HHIP play extremely important anti‐tumour roles in HBV‐positive liver cancer cells." (PMID 32525231, 2020). "Based on analyses using the Human Protein Atlas, TCF21 protein levels were found to be low or absent in liver cancer tissues and were medium in normal liver tissues." (PMID 32525231, 2020).
membranous nephropathy (1 paper, 2023). "The TCF21 staining signal was mainly in the nucleus in the healthy kidney, while in our mild case of membranous nephropathy, the signal increased and appeared in the cytoplasm and brush border of renal tubules." (PMID 36875100, 2023). "DACH1 expression decreased in glomerulus and renal tubule of membranous nephropathy (MN) (P < 0.05), while TCF21 expression increased in MN, especially in the renal tubule cells (P < 0.05)." (PMID 36875100, 2023).
Nephropathy (1 paper, 2023). A nonspecific term referring to disease or damage of the kidneys. "However, in our FA-induced nephropathy murine model, TCF21 mRNA levels were elevated compared to control group." (PMID 36875100, 2023).
nephrotic syndrome (1 paper, 2020). A collection of symptoms that include severe edema, proteinuria, and hypoalbuminemia; it is indicative of renal dysfunction. "Urinary TCF21 level was especially high in nephrotic syndrome but decreased following positive response to treatment." (PMID 32661376, 2020). "In nephrotic rat models, TCF21 expression in podocytes increased along with the severity of nephrotic syndrome." (PMID 32661376, 2020). "Immunohistological analysis suggested the highest TCF21 expression in nephrotic syndrome along with the urinary protein level." (PMID 32661376, 2020). "Finally, we investigated the changes in urinary TCF21 concentration in 29 cases with nephrotic syndrome depending based on treatment response variability." (PMID 32661376, 2020). "Therefore, we confirmed that TCF21 is highly expressed in podocytes of both human and rat glomeruli with nephrotic syndrome." (PMID 32661376, 2020). "In our experiment, Tcf21-MPs showed low moving activity, so we may expect that Tcf21 forces injured podocytes to keep locating at fixed position along the capillary walls in nephrotic syndrome or FSGS." (PMID 32661376, 2020). "Additionally, the glomeruli of patients with nephrotic syndrome revealed that the TCF21 expression in podocytes increased involving the nucleus, the cytoplasm and dendrite." (PMID 32661376, 2020). "To exclude the possibility that some factors such as microvilli or exosome from shed podocytes influence on the urinary TCF21 level, we compared TCF21 concentration of supernatants before and after the removal of microvilli or exosome by ultra-centrifugation in 3 patients with nephrotic syndrome." (PMID 32661376, 2020). "In our study, TCF21 was not expressed in glomerular segmental sclerotic legions (data not shown), and the TCF21 expression score was markedly lower in human FSGS than in other forms of nephrotic syndrome including MCD and MGN." (PMID 32661376, 2020).
Osteochondroma (1 paper, 2019). A common, benign cartiliginous neoplasm arising from the metaphysis of bone. "The results indicated that the positive expression rate of TCF21 protein in OS tissues was significantly lower than that in osteochondroma tissues (29.3% VS 86.7%, P < 0.01)." (PMID 30804710, 2019). "The positive expression rate of TCF21 in OS tissues was significantly lower than that in osteochondroma tissues (25.9% VS 83.3%, P < 0.01)." (PMID 30804710, 2019). "Similarly, the expression of TCF21 in OS tissues and osteochondroma tissues was also detected by ISH." (PMID 30804710, 2019). "In addition, the positive expression rate of TCF21 protein in OS tissues was significantly lower than that in osteochondroma tissues." (PMID 30804710, 2019). "In addition, the expression of TCF21 protein in OS tissues and osteochondroma tissues was detected by immunohistochemistry." (PMID 30804710, 2019).
ovarian diseases (1 paper, 2023). "Some DEGs in F1 ovaries are related to reproductive/ovarian diseases, particularly POI (as Wt1, Bmpr2, Zp1, Zp2) and PCOS (as Tcf21, Fst, Bmpr2)." (PMID 36982971, 2023).
ovarian tumor (1 paper, 2023). "We compared the bulk transcriptomes of hiPSCs, COV434 and KGN ovarian tumor cells, and sorted FOXL2+CD82+ granulosa-like cells from day 5 of a polyclonal differentiation with expression of our previously identified top TFs (NR5A1, TCF21, GATA4, and RUNX1)." (PMID 36803359, 2023).
Paroxysmal atrial fibrillation (1 paper, 2024). Episodes of atrial fibrillation that typically last for several hours up to one day and terminate spontaneously. "Another study found significant associations between the GG genotype and G allele of rs12190287 in TCF21 and an increased TCF21 concentration with the onset and recurrence of paroxysmal atrial fibrillation post ablation." (PMID 38250610, 2024).
pericoronitis (1 paper, 2020). Inflammation of the gingiva surrounding the crown of a tooth. "TCF21 or Transcription factor gene is a tumor suppressor gene and is associated with Uterine Corpus carcinoma and Pericoronitis." (PMID 32894086, 2020).
preeclampsia (1 paper, 2026). Preeclampsia is a hypertensive disorder of pregnancy that is characterized by new-onset hypertension with proteinuria presenting after 20 weeks of gestation, and depending on mild or severe forms may initially present with severe headache, visual disturbances, and hyperreflexia. "In multivariable analysis, urinary TCF21 remained independently associated with preeclampsia (adjusted odds ratio 2.83 per 50 pg/mL; 95% CI 1.49–5.59; p = 0.002), and combined models improved discrimination (AUC 0.87; 95% CI 0.82–0.91)." (PMID 41998596, 2026). "Podocyte injury is implicated in preeclampsia; urinary transcription factor 21 (TCF21) may serve as a non-invasive marker of glomerular involvement." (PMID 41998596, 2026). "CONCLUSIONS: Urinary TCF21 is a novel, non-invasive biomarker associated with preeclampsia and showed a hypothesis-generating inverse association with disease severity." (PMID 41998596, 2026). "Urinary TCF21 demonstrated moderate discrimination for preeclampsia (AUC 0.769) and was inferior to the sFlt-1/PlGF ratio (AUC 0.812)." (PMID 41998596, 2026). "RESULTS: Compared with controls, women with preeclampsia had higher sFlt-1 (11.4-fold; p < 0.001), a higher sFlt-1/PlGF ratio (40.6-fold; p < 0.001), and higher urinary TCF21 (1.7-fold; p < 0.001), with lower PlGF (− 68%; p < 0.001)." (PMID 41998596, 2026).
respiratory failure (1 paper, 2013). The significant impairment of gas exchange within the lungs resulting in hypoxia, hypercarbia, or both, to the extent that organ tissue perfusion is severely compromised. "Studies of TCF21 function in the adult have been hampered since Tcf21 null mice die postnatally due to pulmonary hypoplasia and respiratory failure." (PMID 23874238, 2013).
ST Elevation Myocardial Infarction (1 paper, 2024). A myocardial infarction that produces elevation in the ST segments of the ECG. "Considering these findings, study aimed to further explore whether TCF21 genetic polymorphisms affected susceptibility to stable angina and ST elevation myocardial infarction (STEMI) and their relationships with clinical and biochemical characteristics." (PMID 38250610, 2024).
stable angina (1 paper, 2024). "The precise role of TCF21 polymorphisms in stable angina and STEMI has yet to be confirmed, although chronic inflammatory cytokines have been implicated 38-40." (PMID 38250610, 2024). "The results of the current study indicate that the CC genotype of TCF21 (12190287G/C) polymorphism is associated with stable angina and STEMI." (PMID 38250610, 2024). "More importantly, the rs12190287 C allele may interact with miR-224 leading to a reduction in TCF21 expression through mechanisms linked to miRNA, playing important roles in the risk of stable angina and STEMI." (PMID 38250610, 2024). "Taken together with our findings, TCF21 gene polymorphisms may play important roles with a heritable form of gene-environment interaction in stable angina and STEMI." (PMID 38250610, 2024). "In addition, the cross-sectional design limits our ability to infer a causal relationship between TCF21 gene (12190287G/C) variants and stable angina and STEMI." (PMID 38250610, 2024). "The TCF21 genotype distributions were significantly different between the stable angina and STEMI groups when compared to the control group (p < 0.01)." (PMID 38250610, 2024). "The present study shows that TCF21 gene G/C polymorphism is significantly associated with stable angina and STEMI both in non-adjusted and adjusted models." (PMID 38250610, 2024). "Furthermore, using Pearson's correlation analysis, TCF21 CC genotypes showed positive correlations with stable angina (r = 0.130, p = 0.001) and STEMI (r = 0.203, p < 0.0001), while TCF21 GG genotypes exhibited a negative correlation with STEMI (r = -0.148, p = 0.003)." (PMID 38250610, 2024). "Furthermore, TCF21 CC genotypes showed positive correlations with both stable angina and STEMI, whereas TCF21 GG genotypes exhibited a negative correlation with STEMI." (PMID 38250610, 2024). "Furthermore, TCF21 CC genotypes demonstrated positive correlations with both stable angina and STEMI, while TCF21 GG genotypes exhibited a negative correlation with STEMI." (PMID 38250610, 2024).
Stroke (1 paper, 2020). Sudden impairment of blood flow to a part of the brain due to occlusion or rupture of an artery to the brain. "We identified colocalization signals at several established single trait loci such as TCF21, ADAMTS7, and LIPA for CAD, and NGF, FHL5, TSPAN2, and SLC24A3 for stroke." (PMID 31917787, 2020).
urinary system tumors (1 paper, 2021). "They proposed that combined detection of TCF21 level and PCDH17 methylation is conductive to diagnose urinary system tumors." (PMID 34970358, 2021).
uterine corpus endometrial carcinoma (1 paper, 2021). A endometrial carcinoma (disease) that involves the body of uterus. "First, TCF21 has been revealed in uterine corpus endometrial carcinoma cases according to the microarray studies in 2012." (PMID 35071232, 2021).
Wilms tumor (1 paper, 2015). An embryonal neoplasm characterized by the presence of epithelial, mesenchymal, and blastema components. "We show that CCSKs have a significantly lower TARID expression compared to Wilms tumors, negatively correlating with the level of TCF21 promoter methylation." (PMID 26158413, 2015).
tumor (66 papers, 2007 to 2025). "This study attempted to elucidate the regulatory mechanism of transcription factor 21 (TCF21) on the immunosuppressive effect of tumor-associated macrophages (TAM) in NSCLC." (PMID 37765264, 2023). "Curcumin reduces the activity of a methyltransferase, DNMT1, so modifying the methylation of several tumor-correlated genes and causes an augment of the transcription factor 21 (TCF21)." (PMID 35406692, 2022). "This implies a tumor suppressor function for TCF21, therefore tumor-associated promoter DNA methylation, and possibly transcriptional silencing, are not surprising." (PMID 18616821, 2008). "Other signatures were also identified in this analysis that implicates previously unreported processes in Vκ*MYC disease biology including signatures related to knockdown of the tumour suppressor TCF21, KRAS mutations, and constitutive activation of the RHOA oncogene." (PMID 34732728, 2021). "The epigenetic modification or activation and/or loss of TCF21 expression results in an imbalance in TCF21 signaling, which may lead to tumor initiation and, most likely, to progression and tumor metastasis." (PMID 33729392, 2021). "Gene TCF21 with a large value of jGRP (jGRP = −0.99, p-value < 10−16, BH-corrected p-value < 10−16), which encodes a transcription factor of the basic helix-loop-helix family, was extensively observed as tumor suppressor to under-express in human malignancies." (PMID 28830341, 2017). "Recent research has identified miR‐106b as a tumor suppressor by inhibiting cell migration and invasion, potentially mediated by the upregulation of the TCF21 gene." (PMID 40904706, 2025). "AKAP12 overexpression significantly reduced tumor volume and weight, while this effect was partially abolished by TCF21 knockdown." (PMID 40226362, 2025). "TCF21, a transcription factor that regulates cellular differentiation and organogenesis, has been detected as a tumor suppressor in CRC, and reduced TCF21 expression is associated with poor prognosis." (PMID 37987361, 2023). "Among NSCLC patients, the expression of TCF21 was substantially regulated by the methylation level of TCF21 and was intimately related to tumor staging and tumor metastasis." (PMID 37765264, 2023). "TCF21, which can dampen the ability of tumor invasion, chemoresistance and growth in vivo by regulating the CAF state, was also extensively activated in iCAF cells from primary LUAD." (PMID 36671569, 2023). "Among them, BNC2, SYNM, and TCF21 target genes were detected in all tumor locations, and three targets (GRIK2, KLHL14, and MS4A2) were shared by R-CRC and L-CRC but not by RC." (PMID 37987361, 2023). "As a tumor suppressor, TCF21 exerts an essential role in the development of tumors, and it is considered to be a key regulator of invasion and metastasis of multiple malignant tumors." (PMID 37765264, 2023). "Further studies are warranted to assign to the transcription factor TCF21 the condition of tumor biomarkers and therapeutic targets." (PMID 33729392, 2021). "To explore the biological function of TCF21 in tumor adrenocortical cells, we utilized pCMVMyc-Pod1 transfection to increase TCF21 expression levels in H295R cell line." (PMID 35201460, 2021). "Taken together, these data demonstrate that TCF21 is a tumor suppressor gene epigenetically regulated by promoter methylation." (PMID 33729392, 2021). "TCF21 is involved in tumor initiation, invasion, metastasis, and apoptosis with the molecular mechanisms largely undefined." (PMID 33729392, 2021). "Many pieces of evidence show that TCF21 is regulated by miRNAs, such as miR526b, miR-205, which can inhibit tumor development." (PMID 33004058, 2020). "Research also has shown that TCF21 interferes with the MAPK pathway to inhibit tumor growth, with interaction between specific regions of TCF21 and MAPK." (PMID 31354385, 2019). "The results suggest cross-talk between transcription factors TCF21 with Slug in regulating intrinsic cellular states and tumor subtypes." (PMID 30857227, 2019).
tumor (continued). "On the other hand, TCF21 is found to be deregulated in various types of tumors and functions as a tumor suppressor." (PMID 31354385, 2019). "We observed that a majority of HGSC TMA-cores expressed high-intensity cytoplasmic TCF21, moderate nuclear expression of which was present in ~5–10% of tumor cells." (PMID 30857227, 2019). "TCF21 methylation levels in urine samples were significantly correlated with tumor size, Fuhrman grade, and clinical stage." (PMID 29080283, 2018). "TCF21 is a transcription factor involved in tubular epithelial development of the kidney and is a candidate tumor suppressor." (PMID 29080283, 2018). "One explanation for this behavior is that the loss of TCF21 decreases the activation of the known metastatic suppressor, KISS1, causing an increase in the metastatic potential of the tumor." (PMID 28476165, 2017). "We know that TCF21 is a crucial tumor suppressor, and TCF21 expression is commonly deregulated by aberrant promoter methylation in different types of cancer." (PMID 28515486, 2017). "By promoting TCF21 expression, curcumin impairs tumor progression by inhibiting the emergence of cancer stem cells, thereby containing the cancer dissemination." (PMID 27894084, 2016). "Transcription factor 21 (TCF21) functions as a tumor suppressor and is inactivated in several types of cancer." (PMID 27270650, 2016). "Recently, TCF21 has been identified as a tumor suppressor and inactivated in several types of cancer." (PMID 27270650, 2016). "TCF21 belongs to class II bHLH transcription factors, and is considered as a tumor suppressor, but the detailed mechanism is still unclear." (PMID 27028856, 2016). "We showed that H1299 cells overexpressing TCF21 exhibited a slower tumor growth than normal H1299 in vivo." (PMID 27894084, 2016). "TCF21 overexpression and knockdown was introduced to H1299 cells through lentiviral system, which led to suppression and promotion of tumor growth, respectively." (PMID 27894084, 2016). "After inoculation, we observed that cells with TCF21 overexpression showed a much lower growth rate than those expressing lentivirus vector (P<0.01), as evident by smaller tumor size and lower tumor weight." (PMID 27894084, 2016). "Accordingly, TCF21 overexpression and suppression had pro-tumorigenic and tumor-suppressive effects, respectively." (PMID 27894084, 2016). "Considering the demethylating activity of curcumin, there is possibility that the anti-tumor function of curcumin resides in the upregulation of TCF21." (PMID 27894084, 2016). "Using ccRCC and matched normal kidney samples, it was also evidenced that the increased levels of miR-185 and miR-21 in tumors correlate with the loss of function of specific tumor suppressors such as PTPN13, SLC12A1 and TCF21." (PMID 26670229, 2015). "Transcription factor 21 (TCF21) has been identified as a candidate tumor suppressor at 6q23-q24 that is epigenetically inactivated in many cancers." (PMID 26198328, 2015). "TCF21 has been identified as a candidate tumor suppressor gene and is frequently epigenetically silenced in various human cancers." (PMID 23874238, 2013). "TCF21 has been found to mediate many biological processes by serving as a tumor suppressor." (PMID 40226362, 2025). "However, the positive cells of TCF21, AKAP12, and metastasis marker E-cadherin were reduced, while proliferation marker Ki67-positive cells were enhanced in the tumor tissues of the AKAP12 + sh-TCF21 group." (PMID 40226362, 2025). "The expression of TCF21 seems to be regulated by epigenetic mechanisms, such as methylation, histone acetylation, and SUMOylation, as well as noncoding RNAs (ncRNAs), mostly described in tumor cells." (PMID 33729392, 2021).